PAK5 (p21 (RAC1) activated kinase 5)
Description:
Serine/threonine protein kinase that plays a role in a variety of different signaling pathways including cytoskeleton regulation, cell migration, proliferation or cell survival. Activation by various effectors including growth factor receptors or active CDC42 and RAC1 results in a conformational change and a subsequent autophosphorylation on several serine and/or threonine residues. Phosphorylates the proto-oncogene RAF1 and stimulates its kinase activity. Promotes cell survival by phosphorylating the BCL2 antagonist of cell death BAD. Phosphorylates CTNND1, probably to regulate cytoskeletal organization and cell morphology. Keeps microtubules stable through MARK2 inhibition and destabilizes the F-actin network leading to the disappearance of stress fibers and focal adhesions.
Synonyms: KIAA1264; PAK7
Tractability: Small molecule: a structure with a bound ligand is known; a high-quality ligand is known; it has a high-quality binding pocket; it belongs to a druggable protein family. Antibody: its Gene Ontology location is reachable by antibodies, with high confidence. PROTAC: a small molecule that binds it is known.
Target class: Protein Kinase; STE protein kinase PAKB subfamily; STE protein kinase STE20 family; STE protein kinase group; Enzyme; Kinase
Chemical probes: GNE-2861, PF-03758309
Gene: Protein-coding gene on chromosome 20 (9,537,370 to 9,839,076, reverse strand). Ensembl gene ENSG00000101349.
Subcellular location: Mitochondrion; Cytoplasm; Nucleus
Subcellular location (Human Protein Atlas): Nucleoplasm; Cytosol; Mitochondria; Nuclear membrane
Pathways (Reactome):
Signal Transduction: CDC42 GTPase cycle; RAC1 GTPase cycle; RHOD GTPase cycle; RHOH GTPase cycle
Developmental Biology: Activation of RAC1
Gene Ontology:
Molecular function: protein binding; protein serine/threonine kinase activity; ATP binding; protein kinase activity; protein serine kinase activity
Biological process: apoptotic process; cell migration; cell population proliferation; cellular response to starvation; cytoskeleton organization; regulation of cell growth; regulation of MAPK cascade; signal transduction
Cellular component: cytosol; mitochondrion; nuclear membrane; nucleoplasm; cytoplasm; plasma membrane; nucleus; synapse
Genetic constraint (gnomAD): Loss-of-function variants: 13 observed, 62.85 expected, observed/expected ratio (o/e) 0.21, 90% interval 0.13 to 0.33. The upper end of that interval is the gene's LOEUF score, 0.33, which puts it in group 1 of 6, group 1 being the genes least tolerant of losing a copy. Missense variants: 741 observed, 889.45 expected, observed/expected ratio (o/e) 0.83, 90% interval 0.78 to 0.88. Synonymous variants: 354 observed, 351.13 expected, observed/expected ratio (o/e) 1.01, 90% interval 0.92 to 1.1.
Homologues: Orthologues: chimpanzee PAK5 (99% identical), macaque PAK5 (99% identical), dog PAK5 (97% identical), rabbit PAK5 (95% identical), rat Pak5 (94% identical), mouse Pak5 (94% identical), pig PAK5 (93% identical), tropical clawed frog pak5 (76% identical), zebrafish pak5 (56% identical). Paralogues in human: PAK4 (51% identical), PAK6 (44% identical), PAK1 (29% identical), PAK3 (29% identical), PAK2 (28% identical), MAP3K19 (19% identical), MAP3K1 (18% identical), MAP4K3 (16% identical), STK4 (16% identical), MAP4K5 (16% identical), STK3 (16% identical), TNIK (16% identical), and 23 more.
Diseases named in the same sentence as PAK5 in open-access papers:
PAK5 is named in the same sentence as 50 diseases in open-access papers, as found by Europe PMC text mining. Sharing a sentence is not in itself a finding about the gene and the disease. The quoted sentences say what the papers report.
breast carcinoma (23 papers, 2013 to 2026). "This study evaluated the role of PAK5 in trastuzumab resistance and explored the potential mechanisms underlying the action of PAK5 in trastuzumab resistance for HER2-positive breast cancer." (PMID 40258843, 2025). "The underlying mechanisms of PAK5 on breast cancer cell proliferation, however, still remains to be fully elucidated." (PMID 29041983, 2017). "In this study, we show that PAK5 is highly expressed in breast cancer tissues and the increased PAK5 is significantly associated with breast cancer progression." (PMID 29041983, 2017). "The high expression of PAK5 is associated with HER2-targeted therapy resistance and poor outcomes of breast cancer patients." (PMID 40258843, 2025). "We verified the expression level of PAK5 by using IHC staining in HER2 positive breast cancer patients (n = 58) treated with trastuzumab, and found that patients with high expression of PAK5 were resistant to trastuzumab treatment." (PMID 40258843, 2025). "We also examined the expression of PAK5 in HER2 positive breast cancer cell lines (SK-BR-3, BT474, JIMT-1)." (PMID 40258843, 2025). "To further investigate the molecular basis of PAK5 in breast cancer, we examined the PAK5 expression level in 102 breast cancer specimens using immunoblot analysis." (PMID 40258843, 2025). "Here, we have found that the expression of PAK5 was elevated in clinical HER2-positive breast cancer had poor response to treatment with trastuzumab, which was associated with poor prognosis in breast cancer patients." (PMID 40258843, 2025). "Although previous results suggest promoting function for PAK5 in breast cancer, definitive evidence related to drug resistance in breast cancer has been lacking until this study was performed." (PMID 40258843, 2025). "In HER2-positive breast cancer, elevated expression of PAK5 promotes m6A modification of lncRNA MALAT1 through phosphorylation of the methyltransferase METTL14 at serine 399, thereby stabilizing MALAT1 RNA level." (PMID 40258843, 2025). "Here, we show that high expression of p21-activated kinase 5 (PAK5) is associated with HER2-targeted therapy resistance and poor outcomes of breast cancer patients." (PMID 40258843, 2025). "Stratification analysis showed that the expression of PAK5 protein in breast cancer tissues was positively correlated with clinical N stage (p = 0.0177), metastasis (p = 0.0245), and HER2 status (p = 0.0321)." (PMID 40258843, 2025). "We transfected wild-type PAK5 (PAK5 WT) or kinase-dead PAK5 (PAK5 KM; PAK5 KM equate to PAK5 K478M) into breast cancer cells." (PMID 40258843, 2025). "PAK5 kinase acts on its targets mainly through phosphorylation and we overexpressed PAK5 in breast cancer cells and identified METTL14 with a phosphorylation site at serine 399 using phosphorylation mass spectrometry." (PMID 40258843, 2025). "In HER2-positive breast cancer, elevated expression of PAK5 promotes m6A modification of lncRNA MALAT1 through phosphorylation of the methyltransferase METTL14, thereby stabilizing MALAT1 RNA level." (PMID 40258843, 2025). "DNPEP (an aspartyl protease) is sponged by PAK5 in breast cancer cells, and its overexpression attenuates cell proliferation and invasion in vitro and suppresses tumour growth and metastasis in vivo." (PMID 36993976, 2023). "USP4 (a cysteine protease) has been identified as the downstream target of DNPEP in the PAK5/DNPEP/USP4 regulatory axis in breast cancer." (PMID 36993976, 2023). "Functionally, we demonstrate that PAK5-mediated AIF phosphorylation promotes the proliferation of breast cancer cells and accelerates the growth of breast cancer in vivo." (PMID 33867848, 2021). "PAK5 inhibits the release of AIF from mitochondria in breast cancer cells by decreasing the mitochondria membrane permeability and increasing the membrane potential." (PMID 33867848, 2021).
breast carcinoma (continued). "SHC4 and PAK5 have both been studied in breast cancer, with the former being used as one of 12 gene signatures linking molecular mechanisms to disease prognosis, and the latter being associated with invasion, metastasis, and poor outcome in several cancers." (PMID 32620123, 2020). "PAK5-mediated phosphorylation and nuclear translocation of NF-κB-p65 promote breast cancer cell proliferation in vitro and in vivo." (PMID 30245957, 2018). "In the present study, we used TMA technology and immunohistochemistry to investigate the role of PAK5 in breast cancer." (PMID 29041983, 2017). "Here we aim to confirm the essential roles of PAK5 on cell proliferation after overexpression or knockdown of PAK5 in breast cancer cell BT549 and MDA-MB-231, as well as to provide further insight into the potential mechanism involved." (PMID 29041983, 2017). "To further elucidate molecular mechanisms of PAK5 regulating proliferation and cell cycle in breast carcinoma cells, we performed Western blot to detect the Cyclin D proteins levels in MDA-MB-231 and BT549 cells." (PMID 29041983, 2017). "Our data demonstrated that PAK5 expression was increased in breast cancer tissues compared with tumor adjacent normal breast tissues." (PMID 29041983, 2017). "Because dysregulation of cell cycle and out of control of cell division lead to infinite proliferation of cancer cell to some extent, we examined the effects of PAK5 on proliferation and cell cycle of breast cancer cells." (PMID 29041983, 2017). "Of the 129 breast cancer patients analyzed, low and high PAK5 staining were 43.4% (56/129) and 56.6% (73/129), respectively." (PMID 29041983, 2017). "Growing evidence suggest that the signal pathways of p21cdc42/rac1-activated kinase 5 (PAK5) have been found in various tumor progression, however, the role of PAK5 in breast cancer remains largely unclear." (PMID 29041983, 2017). "Our data revealed that high PAK5 staining correlated with worse overall survival in breast cancer (P = 0.0192)." (PMID 29041983, 2017). "Since PAK5 and PAK6 proteins are less frequently associated with breast cancer, our focus for this study was PAK4, but further investigation is warranted." (PMID 28198380, 2017). "Our data provide important insight into the PAK5-p65 signals in regulating Cyclin D1 to promote breast cancer growth." (PMID 29041983, 2017). "Taken together, our results showed that PAK5 is expressed at high levels in breast cancer tissue and that increased PAK5 was significantly correlated with breast cancer progression and was a prognostic factor of worse outcome in breast cancer patients." (PMID 29041983, 2017). "Our previous studies also suggested that PAK5 contributed to proliferation and cell cycle regulation in breast cancer." (PMID 29041983, 2017). "An increasing body of evidence suggests that increased expression of PAK5 was observed in a variety of human malignancies including breast cancer, colorectal cancer, stomach cancer, pancreatic cancer, neuroblastoma, osteosarcoma and epithelial ovarian cancer." (PMID 29041983, 2017). "Taken together, PAK5 can augment the expression of Cyclin D1 and Cyclin D3 and inhibit the expression of p21 and p27, accelerating cell-cycle progression in breast cancer cells." (PMID 29041983, 2017). "Knockdown of PAK5 inhibited human breast cancer cell proliferation by inducing cell cycle arrest in G0/G1 phase, which is generally in concordance with the downregulation of Cyclin D1." (PMID 29041983, 2017). "Xenograft models in nude mice were established to explore the roles of PAK5 in breast cancer growth." (PMID 29041983, 2017). "Knockdown of PAK5 inhibited EMT mediated by GATA1-HDAC3/4 complex in breast cancer cells (compare lane 5 with lane 2 or compare lane 6 with lane 3)." (PMID 25726523, 2015). "In addition, patients with high PAK5 expression breast cancer who received trastuzumab had poor overall survival (OS) and disease-free survival (DFS)." (PMID 40258843, 2025).
breast carcinoma (continued). "To gain mechanistic insight into the function of the PAK5-MALAT1-nuclear HER2 in breast cancer, we wondered whether MALAT1 regulated HER2 mRNA." (PMID 40258843, 2025). "Importantly, PAK5 promotes the therapeutic resistance of HER2-positive breast cancer cells by increasing N-HER2 protein both in vitro and vivo." (PMID 40258843, 2025). "In addition, the endogenous interaction of PAK5 with METTL14 was demonstrated in SK-BR-3 breast cancer cells." (PMID 40258843, 2025). "Interestingly, a higher level of PAK5 protein was observed in the intrinsically trastuzumab-resistant JIMT-1 breast cancer cells compared to the trastuzumab-sensitive SK-BR-3 and BT474 cells." (PMID 40258843, 2025). "Additionally, PAK5 inhibits the therapeutic response of HER2-positive breast cancer cells to trastuzumab in vitro and in vivo." (PMID 40258843, 2025). "Although p21 activated kinase 5 (PAK5) is related to the progression of multiple cancers, its biological function in breast cancer remains unclear." (PMID 33867848, 2021). "PAK5-mediated GATA-1 phosphorylation regulates EMT in breast cancer cells." (PMID 31783675, 2019). "Considering that PAK5 also regulated cell migration and invasion in cancer types such as colon cancer, bladder cancer, and breast cancer, other publication and our findings might implicate that PAK5 had a wide role in regulating solid tumor progression." (PMID 30245957, 2018). "Taken together, our findings suggest that PAK5 may serve as a potential prognosis marker and therapeutic target for human breast cancer." (PMID 29041983, 2017). "However, it remains to be elucidated how PAK5 regulates Cyclin D1 in breast cancer cell proliferation." (PMID 29041983, 2017). "Furthermore, we demonstrated the activated p65 via PAK5-mediated phosphorylation interacted with Cyclin D1 promoter to promote cell proliferation of breast cancer cells." (PMID 29041983, 2017). "Our results firstly provided the evidences that PAK5 might represent a new therapy to suppress breast cancer uncontrolled proliferation in vitro as well as in vivo." (PMID 29041983, 2017). "In the following experiment, we further investigated whether cell cycle of breast carcinoma cells changes resulting from regulation of PAK5 expression." (PMID 29041983, 2017). "Furthermore, xenograft models in nude mice were established to explore the roles of PAK5 in breast cancer growth." (PMID 29041983, 2017). "However, the relationships of between the co-expression of PAK5/p65 and patients with breast cancer are ambiguous; and the specific PAK5 phosphorylation sites in p65, still remain to be substantiated." (PMID 29041983, 2017). "Importantly, the high level of PAK5 expression correlated with the expression of GATA1 in breast cancer tissues (p = 0.033)." (PMID 25726523, 2015). "However, it is unknown whether PAK5 is involved in trastuzumab resistance in HER2-positive breast cancer." (PMID 40258843, 2025). "Our results showed that increased PAK5 expression was closely associated with pT status, pN status and TNM stage, which suggest that PAK5 may play an important role in the breast cancer development and progression, as well as may serve as a molecular prognostic marker for this disease." (PMID 29041983, 2017). "Our results indicate that PAK5 phosphorylates METTL14 at serine 399 and the phosphorylation of METTL14 S399 site in breast cancer tissues is more active than that in normal tissues." (PMID 40258843, 2025). "P21-activated kinase 5 (PAK5), a member of the PAK family of Ser/Thr kinases, phosphorylates a variety of proteins to promote breast cancer cell proliferation and metastasis." (PMID 40258843, 2025). "PAK5 phosphorylates AIF at Thr281 and prevents the formation of a complex between AIF and importin α3 in breast cancer cells, resulting in the decreased nuclear translocation of AIF." (PMID 36830998, 2023). "PAK5 phosphorylates apoptosis-inducing factor (AIF) in breast cancer and promotes breast cancer progression." (PMID 36830998, 2023).
breast carcinoma (continued). "Significantly, PAK5 and AIF expression in breast cancer are positively correlated with poor patient prognosis." (PMID 33867848, 2021). "We further investigate the relationship between PAK5 and p65 expression and results show that PAK5 and p65 are positively related to each other (r = 0.326, P < 0.05), which implies that the coordination between PAK5 and p65 expression may have a positive impact on breast cancer progression." (PMID 29041983, 2017). "Based on these results, we propose that the phosphorylated GATA1 by PAK5 recruits more HDAC3/4 to the E-cadherin promoter, thus promotes transcriptional repression of E-cadherin, leading to the EMT of breast cancer cells." (PMID 25726523, 2015). "The high expression rate of the PAK5 and GATA1 were 66.25% (53/80) and 62.50% (50/80) in breast cancer tissues and low expression rate 33.75% (27/80) and 37.50% (30/80) in matched adjacent noncancerous tissues." (PMID 25726523, 2015). "Meanwhile, we showed that phosphorylated GATA1 by PAK5 recruits more HDAC3/4 to promote transcriptional repression of E-cadherin, leading to the EMT of breast cancer cells." (PMID 25726523, 2015). "Importantly, PAK5 and HER2, especially N-HER2, were co-overexpressed in trastuzumab-resistant breast cancer tissues." (PMID 40258843, 2025). "However, we have not tested the effects of KPT-9274 on the other group II PAK family members, PAK5 and PAK6, in breast cancer cells." (PMID 28198380, 2017). "We evaluated PAK5 and p65 staining in breast cancer tissues (BCTs) and paired non-cancerous tissues (NTs) using tissue microarray (TMA) technology." (PMID 29041983, 2017). "Inversely, knocking down endogenous PAK5 dramatically restrained proliferative ability in both breast cancer cell lines compared with the negative control." (PMID 29041983, 2017). "PAK5 was in higher expression in breast cancer tissues than matched adjacent noncancerous tissues, which was consistent with the previous report." (PMID 25726523, 2015). "It has been reported that Akt directly phosphorylated GATA1 at serine 310, and PAK5 was in higher expression in breast cancer tissues than matched adjacent noncancerous tissues." (PMID 25726523, 2015). "Furthermore, the PAK5-AIF signaling pathway may play an essential role in mammary tumorigenesis, providing a new therapeutic target for breast cancer treatment." (PMID 37014322, 2023). "However, the PAK5 expression status and its correlation with the clinicopathologic features in breast cancer have never been illuminated." (PMID 29041983, 2017). "PAK5 phosphorylates the transcription factor GATA1 mainly at Ser161 and Ser 187, phosphorylated GATA1 recruits more HDAC3/4 to the promoter of E-cadherin and consequently suppresses the transcription of E-cadherin gene and promotes the EMT of breast cancer cells." (PMID 25726523, 2015). "In the current study, we evaluated PAK5 and p65 staining in breast cancer tissues (BCTs) and paired non-cancerous tissues (NTs) using tissue microarray (TMA) technology and analyzed the correlation between PAK5 as well as p65 expression and clinicopathologic features." (PMID 29041983, 2017).
colorectal cancer (9 papers, 2014 to 2026). A primary or metastatic malignant neoplasm that affects the colon or rectum. "Emerging evidence indicates that Wnt/β-catenin signaling upregulates SATB1 to drive colorectal cancer initiation and progression, while PAK5-mediated phosphorylation enhances its oncogenic potential in cervical cancer." (PMID 41208974, 2025). "The high expression of PAK5 in ovarian cancer was basically in accordance with that in glioma and in colorectal carcinoma." (PMID 30245957, 2018). "It is reported that PAK5 regulates cell adhesion and migration in colorectal carcinoma cells." (PMID 25726523, 2015). "In colorectal cancer, SRSF11 interacts with PAK5, promoting alternative splicing of HSPA12A, which supports proliferation and invasion." (PMID 41584036, 2026). "MiRNA 129 has been reported to have great potential as a therapeutic agent in select tumors including bladder cancer, colorectal cancer, gastric cancer, and lung cancer, and may inhibits cancer cell proliferation, metastasis and invasion through targeting relevant genes such as ETS1, CDK6, PAK5." (PMID 27050373, 2016).